GCKR (glucokinase regulator)
Diseases named in the same sentence as GCKR in open-access papers (continued):
Sharing a sentence is not in itself a finding about the gene and the disease.
breast carcinoma (2 papers, 2017 to 2025). "Carriers of the GCKR rs780094 C major-allele had an association with increased risk of breast cancer in women with w/h > 0.85; approximately 50% of cancer risk attributable to this variant was mediated via glucose levels in this obese group." (PMID 28446149, 2017). "It is notable that among obese women, 50% of cancer risk was mediated via glucose metabolism trait, owing to two SNPs: in breast cancer, in relation to GCKR through glucose, and in CRC, in relation to DGKB/TMEM195 through HOMA-IR." (PMID 28446149, 2017). "In relation to breast cancer risk, obese carriers of G6PC2, IGF1, and GCKR had an association with increased risk." (PMID 28446149, 2017).
carotid atherosclerosis (2 papers, 2021 to 2024). A thickening and loss of elasticity of the walls of carotid arteries that occur with formation of atherosclerotic plaques. "Another study reported that CC homozygosity of the GCKR gene and plasma TG concentrations are independently associated with subclinical carotid atherosclerosis in women with SLE." (PMID 39877363, 2024). "In this study, the analysis of the ZPR1, APOA5, and GCKR genes in patients with SLE, showed that GCKR rs1260326 is strongly related to the presence of carotid atherosclerosis." (PMID 34065555, 2021).
diabetic nephropathy (2 papers, 2013 to 2025). "Current research has found that diabetic nephropathy is associated with the rs780094 polymorphism in the glucokinase regulatory protein (GCKR) gene, but the specific molecular mechanisms remain to be elucidated." (PMID 40061454, 2025). "The study confirms the findings of previous studies showing the association of UMOD with eGFR and diabetic nephropathy 12–15 and the association of GCKR and SHROOM3 with eGFR 1,16,17." (PMID 23586973, 2013).
liver cirrhosis (2 papers, 2021 to 2025). "PNPLA3 has not only been associated with the development of liver cirrhosis and HCC, but has also shown a stronger association when compared with other risk alleles (e.g., SERPINA1, TM6SF2, MBOAT7 or GCKR)." (PMID 33804385, 2021).
myocardial infarction (2 papers, 2018 to 2020). Gross necrosis of the myocardium, as a result of interruption of the blood supply to the area, as in coronary thrombosis. "First, the meta-analysis of the association of GCKR with CAD depends to a large extent on the the combined UK Biobank, CARDIoGRAMplusC4D 1000 genomes-based GWAS, and Myocardial Infarction Genetics and CARDIoGRAM Exome dataset, which is actually a meta-analysis by itself." (PMID 30352097, 2018).
non-alcoholic steatohepatitis (2 papers, 2017 to 2019). "Interestingly, a recent report demonstrated that a rare loss-of-function variant Arg227Ter of GCKR was associated with a rapidly progressive form of nonalcoholic steatohepatitis giving further evidence on the role of GCKR in liver diseases." (PMID 31308433, 2019).
adult T-cell leukemia/lymphoma (1 paper, 2022). A peripheral (mature) T-cell neoplasm linked to the human T-cell leukemia virus type 1 (HTLV-1), adult T-cell leukemia/lymphoma is endemic in several regions of the world, in particular Japan, the Caribbean, and parts of Central Africa. "In adult T-cell leukemia/lymphoma (ATL), HDAC8 expression was driven by an oncogenic cascade of FRA-2/JUND and SOX4 transcription factor, and— together with other two activated genes, GCKR and NAP1—was proven to affect ATL cell growth." (PMID 35887172, 2022).
alcoholic fatty liver disease (1 paper, 2021). Lipid infiltration of the hepatic parenchymal cells that is due to alcohol abuse. "In 74 patients with non-alcoholic fatty liver disease from Tabriz city in the north-west of Iran, the lack of association between the GCKR rs780094 genotypes and lipid profile was observed." (PMID 33602293, 2021).
cholelithiasis (1 paper, 2025). The presence of crystallized deposits forming in the gallbladder or biliary tree, primarily composed of cholesterol, bilirubin, and bile. "Seven genes, including GCKR, SNX17, ABCG8, MARCH8, FUT2, APOH, and HNF1A, were revealed to be colocalized with the causal signal between sphingomyelin and cholelithiasis." (PMID 40428345, 2025).
colorectal cancer (1 paper, 2023). A primary or metastatic malignant neoplasm that affects the colon or rectum. "Among them, GCKR has not been reported as a prognostic biomarker so far; only two studies have reported that gastric and colorectal cancer patients with GCKR variates harbored a better prognosis than those of wildtype, and our study revealed its prognostic value in gliomas for the first time." (PMID 36494582, 2023).
COVID-19 (1 paper, 2024). A disease caused by infection with severe acute respiratory syndrome coronavirus 2. "With these observations, the function of GCKR demands a deeper understanding of COVID-19 effects in critical young patients." (PMID 38666857, 2024).
depression (1 paper, 2024). "In this study, two proteins (CSPG3 and GCKR) were linked with eight NAFLD risk factors (BMI, waist circumference, smoking initiation, major depression, iron levels, C-reactive protein levels, galectin-3, and HDL cholesterol)." (PMID 38782984, 2024). "Our study suggested that GCKR may affect NAFLD through modifiable risk factors, such as waist circumference, smoking, depression, C-reactive protein levels, galectin-3, and HDL cholesterol." (PMID 38782984, 2024).
diffuse large B-cell lymphoma (1 paper, 2025). "Notably, in BRCA, diffuse large B-cell lymphoma (DLBC), and LUAD, high GCKR expression predicted unfavorable outcomes, whereas in gastric cancer, reduced GCKR expression was correlated with poorer prognosis." (PMID 41235343, 2025).
endometriosis (1 paper, 2025). The growth of functional endometrial tissue in anatomic sites outside the uterine body. "Endometriosis-associated SNP-SNPinter models include 7 SNPs from 9 analyzed loci, such as rs17496332 (A > G) PRMT6, rs780093 (C > T) GCKR, rs10454142 (T > C) PPP1R21, rs3779195 (T > A) BAIAP2L1, rs440837 (A > G) ZBTB10, rs7910927 (G > T) JMJD1C, and rs8023580 (T > C) NR2F2." (PMID 41373783, 2025).
esophageal cancer (1 paper, 2024). A primary or metastatic malignant neoplasm involving the esophagus. "Although the impact of ADH1B on esophageal cancer risk is well documented, this is the first identification of the genetic contribution of the other four (GCKR, KLB, ALDH1A1, and ALDH2) to esophageal cancer risk." (PMID 38277453, 2024). "The rs671 genotype stratification revealed that contributions to esophageal cancer risk from GCKR, ALDH1A1, and ALDH2 might be observable exclusively among heterozygotes." (PMID 38277453, 2024). "Of these, four (GCKR, ADH1B, ALDH1A1, and ALDH2) were found to potentially interact with rs671 on the risk of esophageal cancer." (PMID 38277453, 2024). "Of the discovered loci, four (GCKR, ADH1B, ALDH1A1, and ALDH2) were suggested to interact with rs671 in the risk of esophageal cancer, a representative alcohol-related disease." (PMID 38277453, 2024). "The interaction analysis further highlighted the potential combined effect of GCKR, ADH1B, ALDH1A1, and ALDH2 with rs671 GA toward increased (GCKR, ADH1B, and ALDH1A1) or decreased (ALDH2) risk of esophageal cancer and thereby carries important implications for personalized prevention." (PMID 38277453, 2024).
gallstones (1 paper, 2018). Solid crystalline precipitates in the biliary tract, usually formed in the gallbladder, resulting in the condition of cholelithiasis. "In addition, among the reported gallstone loci, the glucokinase regulatory protein (GCKR) is a regulator of glucokinase (GCK), that is linked to MODY2 (OMIM:125851)." (PMID 30504769, 2018).
gastric cancer (1 paper, 2025). A primary or metastatic malignant neoplasm involving the stomach. "In gastric cancer, consistent downregulation of GCKR expression further supported its diagnostic utility." (PMID 41235343, 2025). "Functionally, reduced GCKR expression in gastric cancer was associated with an immune-cold phenotype characterized by diminished cytotoxic T cell infiltration, impaired antigen presentation, and metabolic reprogramming." (PMID 41235343, 2025). "This study presents the first comprehensive pan-cancer analysis of the expression patterns, mutational characteristics, and mechanistic implications of GCKR across multiple cancer types, with a particular emphasis on how metabolic regulation intersects with immune remodeling in gastric cancer." (PMID 41235343, 2025). "This multiomics and experimentally validated study identifies GCKR as a key link between metabolic reprogramming and immune regulation in gastric cancer." (PMID 41235343, 2025). "We then focused specifically on the expression patterns of GCKR in gastric cancer and validated its expression experimentally." (PMID 41235343, 2025). "Single-cell transcriptomic analysis of gastric cancer revealed marked heterogeneity in GCKR expression across cell types." (PMID 41235343, 2025). "Western blotting further validated the downregulation of GCKR protein in tumor tissues, and qRT-PCR confirmed reduced mRNA expression levels in gastric cancer samples." (PMID 41235343, 2025). "ELISA results also indicated significantly lower GCKR levels in gastric cancer (p < 0.05)." (PMID 41235343, 2025). "IHC confirmed lower GCKR expression in gastric cancer tissues compared to adjacent nontumor tissues, particularly in mucosal and basal regions (p < 0.05)." (PMID 41235343, 2025). "Second, although GCKR expression was experimentally validated in gastric cancer, comparable validation in other tumor types was not performed and will be necessary to strengthen the generalizability of our conclusions." (PMID 41235343, 2025).
hypogonadism (1 paper, 2025). A disorder characterized by decreased function of the gonads. "Protein-coding variants in several liver genes, such as PNPLA3, GCKR, SLCO1B1, SERPINA1, HGFAC, and UGT2B15, were significantly associated with total testosterone levels and hypogonadism risk." (PMID 40316537, 2025).
lung adenocarcinoma (1 paper, 2025). A carcinoma that arises from the lung and is characterized by the presence of malignant glandular epithelial cells. "GCKR expression was downregulated in most tumors but upregulated in subsets such as kidney renal papillary carcinoma (KIRP) and lung adenocarcinoma (LUAD)." (PMID 41235343, 2025).
maturity-onset diabetes of the young (1 paper, 2021). "GCKR is the susceptibility gene candidate of maturity-onset diabetes of the young (MODY), whose protein product binds non-covalently to form an inactive complex with the enzyme to regulate glucokinase in liver and pancreatic islet cells." (PMID 34830198, 2021).
melanoma (1 paper, 2018). A malignant, usually aggressive tumor composed of atypical, neoplastic melanocytes. "This list included several oncogenes, namely MIR544A, MIR146B, FAM83A (also known as tumor antigen BJ‐TSA‐9), the cancer‐germline genes PBK (PDZ binding kinase) and PRAME (preferentially expressed antigen in melanoma), and GCKR that, with PRAME, is a downstream target of the BCR‐ABL protein." (PMID 29575763, 2018).
pancreatic cancer (1 paper, 2021). "Also, the GCKR variation has been associated with the risk of pancreatic cancer and the prognosis of metastatic gastric cancer, but no published study so far has examined its association with CRC risk." (PMID 34692549, 2021).
prediabetes (1 paper, 2022). "In this research, only rs1260326 in GCKR was detected in the Korean population and showed a strong association with the risk of prediabetes and T2DM." (PMID 35740093, 2022).
rectum adenocarcinoma (1 paper, 2025). An adenocarcinoma arising from the rectum. "ROC curve analyses revealed that GCKR effectively distinguished tumor from normal tissues in several cancers, including CHOL, liver hepatocellular carcinoma (LIHC), and rectum adenocarcinoma (READ), with AUC values approaching or exceeding 0.85." (PMID 41235343, 2025).
sarcoma (1 paper, 2025). A usually aggressive malignant neoplasm of the soft tissue or bone. "Mutation rates of GCKR and other common oncogenes/tumor suppressors across various cancers indicated relatively high mutation frequencies in sarcoma (SARC) and uterine corpus endometrial carcinoma (UCEC)." (PMID 41235343, 2025).
Tremor (1 paper, 2024). An unintentional, oscillating to-and-fro muscle movement about a joint axis. "Whether the tremor associated with the GCKR variant is a phenocopy or typical ET needs to be investigated further." (PMID 38671141, 2024).
cardiovascular disease (11 papers, 2010 to 2025). "Postprandial triglyceridemia is an emerging risk factor for cardiovascular disease and GCKR gene polymorphisms affect postprandial lipemic response in a dietary intervention study." (PMID 38969939, 2024). "Lead SNPs nearby GCKR, FTO, ZPR1, and APOE were associated with various traits including cardiovascular diseases and/or PhenoAge biomarkers." (PMID 34038024, 2021).
metabolic disease (6 papers, 2023 to 2025). A congenital disorder (due to inherited enzyme abnormality) or acquired (due to failure of a metabolically important organ) disorder resulting from an abnormal metabolic process. "As next-generation sequencing develops, there are significant associations between glucokinase regulatory protein (GCKR) variants and many diseases, especially metabolic diseases." (PMID 41150798, 2025). "Two common variants in the GCKR gene, rs780094 (C>T) and rs1260326 (C>T), have been closely linked to a variety of metabolic diseases." (PMID 37711901, 2023). "The GCKR rs1260326 genetic variant contributed to the impaired hepatic lipid and glucose metabolism and promoted the development of metabolic disorders including NAFLD and T2DM." (PMID 37829557, 2023). "CRP is the prototype acute-phase reactant and a hallmark of low-grade systemic inflammation, thus it has been assumed that chronic low-grade systemic inflammation mediates the effect of the GCKR variant on complex metabolic diseases, including NAFLD." (PMID 36904112, 2023). "Taken together, these insights show that GCKR/GKRP is significantly associated with many metabolic diseases via its complex metabolism system and is a potential target in many metabolic diseases." (PMID 41150798, 2025).
cancer (5 papers, 2017 to 2025). A tumor composed of atypical neoplastic, often pleomorphic cells that invade other tissues. "Glucokinase regulatory protein (GCKR) is a metabolic regulator implicated in glucose homeostasis, but its genetic and functional roles in cancer remain poorly understood." (PMID 41235343, 2025). "Using Spearman's correlation, we explored associations between GCKR and functional proteins involved in cancer progression." (PMID 41235343, 2025). "Analysis of mutation types showed that missense mutations were the most frequent single nucleotide variant (SNV) type in both GCKR and other cancer-related genes, with BRCA exhibiting the highest mutation rate." (PMID 41235343, 2025). "We analyzed the expression and mutation profile of GCKR in cancer, along with its associations with clinical features, immune infiltration, and drug sensitivity." (PMID 41235343, 2025). "The nature of these associations varied across cancers, highlighting the immune-specific role of GCKR." (PMID 41235343, 2025). "GCKR mRNA expression was positively associated with fibroblasts, macrophages, and monocytes in many cancers, pointing to a potential role in shaping the immune microenvironment and contributing to cancer progression." (PMID 41235343, 2025). "Our findings also suggest that GCKR is a prognostic risk factor in cancers such as GBMLGG and GBM." (PMID 41235343, 2025). "Interestingly, the nature of GCKR's associations with immune factors varied between cancers, indicating possible tumor-specific immunomodulatory roles." (PMID 41235343, 2025). "GCKR plays a fundamental role in human glucose metabolism and is involved in various pathophysiological processes, yet its role in cancer has seldom been explored." (PMID 41235343, 2025). "GSEA revealed enrichment of cancer- and metabolism-related pathways in the GCKR high-expression group." (PMID 41235343, 2025). "Despite employing multiomics integration to systematically explore GCKR's roles across cancers, several limitations should be acknowledged." (PMID 41235343, 2025). "Using various immune infiltration algorithms, we found that GCKR expression was positively correlated with fibroblasts, macrophages, and monocytes in several cancers, suggesting a role in modulating the tumor immune microenvironment." (PMID 41235343, 2025). "We evaluated the relationship between GCKR and 14 cancer-related functional pathways by calculating combined z-scores for each gene set (e.g., angiogenesis, apoptosis, EMT, and DNA repair)." (PMID 41235343, 2025). "Using the GDSC database, we analyzed the impact of GCKR on commonly used chemotherapeutic drugs in cancer." (PMID 41235343, 2025). "The results revealed significant differences in GCKR expression between tumor and normal tissues across various cancers." (PMID 41235343, 2025). "Using a pan-cancer analysis strategy, this study systematically characterizes the expression pattern of GCKR across multiple tumor types, evaluates its prognostic significance, and explores its association with the immune microenvironment." (PMID 41235343, 2025). "Notably, GCKR expression also correlated strongly with functional cancer-related proteins in several cancers." (PMID 41235343, 2025). "As malignancy increases, GCKR expression rises in cancers such as KIPAN, KIRC, and PAAD." (PMID 41235343, 2025). "Taken together, our results suggest that GCKR is not only a central regulator in glucose metabolism but may also contribute to cancer development through metabolic–immune interactions." (PMID 41235343, 2025). "Another gene is GCKR, which play a significant role in cancer cell metabolism." (PMID 32272578, 2020). "In contrast, the GCKR variant’s effect on cancer was mediated through glucose by 50% in obese women (but not in non-obese women), indicating that an adiposity-related carcinogenetic pathway in this variant intermingles with the glucose-intolerance system." (PMID 28446149, 2017).
cancer (continued). "This differential pattern suggests GCKR may serve as a potential biomarker for cancer diagnosis." (PMID 41235343, 2025). "Analysis of the tumor immune microenvironment showed significant correlations between GCKR and chemokines, their receptors, immune suppressive and stimulatory factors, and MHC molecules across several cancers." (PMID 41235343, 2025). "Our findings indicate that GCKR expression is lower in most tumors compared with normal tissues, notably in BRCA and CHOL, but elevated in cancers such as KIRP and LUAD." (PMID 41235343, 2025). "GCKR was positively correlated with chemokines, chemokine receptors, immune stimulators, immune inhibitors, and MHC molecules in cancers such as BRCA, THCA, and PRAD." (PMID 41235343, 2025).
genetic disease (1 paper, 2019). "NASH is also a genetic disease; certain genes—including those encoding patatin-like phospholipase domain-containing 3 (PNPLA3), transmembrane 6 superfamily 2 (TM6SF2), and glucokinase regulatory protein (GCKR)—have been implicated as predisposing to its progression to NASH." (PMID 31775341, 2019).